ENPP1 (ectonucleotide pyrophosphatase/phosphodiesterase 1)
Diseases named in the same sentence as ENPP1 in open-access papers (continued):
Sharing a sentence is not in itself a finding about the gene and the disease.
hypophosphatasia (6 papers, 2014 to 2026). Hypophosphatasia (HPP) is a rare heritable metabolic disorder characterized by defective mineralization of bone and/or teeth in the presence of reduced activity of unfractionated serum alkaline phosphatase (ALP). "Mutations that lead to ENPP1 dysfunction result in hypophosphatasia, characterized by generalized arterial calcification of infancy (GACI), and plasma PPi levels are often reduced in patients with ESKD." (PMID 41368304, 2025). "Biallelic pathogenic variants of Ectonucleotide pyrophosphatase/phosphodiesterase 1 (ENPP1) have been identified in patients with a third FGF-23 mediated hypophosphatasia called ‘Autosomal Recessive Hypophosphatemic Rickets type 2’ (ARHR2: OMIM #613,312)." (PMID 37530996, 2023). "Genetics confirmed a homozygous pathogenic variant c.783C>G p.(Tyr261*) in ENPP1 and a heterozygous pathogenic ALPL variant consistent with hypophosphatasia." (PMID 41445557, 2025). "In conclusion, related monogenic disorders of hypophosphatasia and acromegaly should be screened in the clinical assessment of patients with OPLL/DISH, and plasma PPi is a new biomarker enabling clinicians to screen OPLL/DISH patients for ENPP1 deficiency." (PMID 37530996, 2023). "To further understand mechanisms underlying craniosynostosis development in hypophosphatasia, here we sought to determine if craniofacial abnormalities including craniosynostosis and skull shape defects would be alleviated in TNAP null mice by genetic ablation of ENPP1." (PMID 35909501, 2022).
osteoarthritis (6 papers, 2005 to 2025). A noninflammatory degenerative joint disease occurring chiefly in older persons, characterized by degeneration of the articular cartilage, hypertrophy of bone at the margins and changes in the synovial membrane. "This prompted us to perform a family-based association study to test the hypothesis that genetic variation at the ENPP1 locus is involved in the etiology of osteoarthritis of the hand." (PMID 16207325, 2005). "Thus, our data highlights variability of ENPP1 as an important genetic factor in the pathogenesis of idiopathic osteoarthritis." (PMID 16207325, 2005).
enthesopathies (5 papers, 2022 to 2025). "Biochemical assays revealed that the N179S and Y451C ENPP1 variants reduced enzyme velocity by 45% and 30%, respectively, suggesting that decreased PPi could account for the observed spinal enthesopathies." (PMID 37871131, 2024). "A recent study demonstrated that recombinant ENPP1 normalized plasma PPi and prevented enthesopathies in murine biallelic ENPP1 deficiency, also supporting the hypothesis that plasma PPi levels prevent enthesopathies [41•]." (PMID 37530996, 2023). "Biallelic ENPP1 mutations, although rare, induce severe spinal ligament ossifications, whereas patients with monoallelic ENPP1 pathogenic variants exhibit less severe spinal enthesopathies and have a reduced genetic risk of DISH and OPLL." (PMID 37530996, 2023). "The appearance of enthesopathies in both young ARHR2 patients and ttw mice strongly supports ENPP1 as a genetic risk factor for the development of spinal enthesopathies present in OPLL." (PMID 37530996, 2023). "Additionally, a third patient with compound biallelic ENPP1 pathogenic variants (rs2273411/rs20159006) exhibited severe DISH/OPLL and enthesopathies in the Achilles’ tendon and around hip joints [107••]." (PMID 37530996, 2023). "This study also evaluated the presence of ectopic ossifications in family members of probands, identifying 23-year-old and 19-year-old male siblings harboring monoallelic ENPP1 pathogenic variants who also possessed slight Achilles tendon enthesopathies but not OPLL." (PMID 37530996, 2023). "Finally a therapeutic biologic ENPP1-Fc may be a promising therapy for patients suffering from spinal enthesopathies such as OPLL/DISH." (PMID 37530996, 2023).
glioblastoma (5 papers, 2019 to 2024). The most malignant astrocytic tumor (WHO grade IV). "Knockdown of ENPP1 in glioblastoma stem-like cells downregulates stem cell-associated genes, induces tumor differentiation, cell death, and sensitization to chemotherapeutic treatment." (PMID 33635867, 2021). "ENPP1 gene may play a key role in maintaining the malignancy and proliferative activity of glioblastoma cells, which has been verified in the study of glioblastoma." (PMID 33635867, 2021). "However, a few studies have shown that some NM enzymes are functionally involved in de-differentiation processes, like the ecto-nucleotidase ENPP1 in the maintenance of the CSCs-like state in glioblastoma." (PMID 30737477, 2019). "In agreement with RNA data of the Human Protein Atlas, we found ENPP1 protein expression on the glioblastoma cell line U87, but not on the pro-monocytic myeloid leukemia cell line U937." (PMID 39694917, 2024).
hearing loss (5 papers, 2016 to 2025). "Hearing impairment is frequent in patients with ENPP1-deficient GACI, ranging from mild to moderate CHL, and less commonly, SNHL." (PMID 35854274, 2022). "This is the first study to systematically characterize hearing impairment in patients with GACI due to ENPP1 deficiency." (PMID 35854274, 2022). "In addition to ARHR2 and GACI, patients with a pathogenic variant in ENPP1 gene can exhibit hearing loss, OPLL, PXE, and thrombocytopenia, hypoglycemia, neurologic or hepatic manifestations." (PMID 35966073, 2022). "Additionally, early-onset hearing loss may be linked to GACI caused by ENPP1 mutations, and this connection appears to be multifactorial." (PMID 38248755, 2023). "Since patients with ENPP1-deficiency can manifest various phenotypes including GACI, hearing loss, OPLL, and PXE, systematic evaluation should be mandatory for patients diagnosed with ARHR2." (PMID 35966073, 2022).
hepatoma (5 papers, 2018 to 2023). "Insulin-stimulated Akt phosphorylation in HuH7 human hepatoma cells was improved when ENPP1 expression was silenced using siRNA." (PMID 34208364, 2021). "In this study, the mRNA expression level of Enpp1 was examined in the liver samples of rats going through fasting and refeeding cycles, and in primary rat hepatocytes and human hepatoma cells treated with insulin and dexamethasone." (PMID 29513794, 2018). "This led us to observe that the expression of Enpp1 in rat primary hepatocytes and human hepatoma cells is regulated by insulin and glucocorticoid." (PMID 29513794, 2018). "To determine whether the observed hormonal regulations are not limited to primary rat hepatocytes, we used real-time PCR to examine the effects of insulin and dexamethasone on the Enpp1 mRNA abundance in HepG2 cells, a human hepatoma cell line." (PMID 29513794, 2018). "As the enzymatic activity of ENPP1 seems to be needed for its inhibitory effect on insulin signaling, the suppression of Enpp1 mRNA abundance by insulin in primary rat hepatocytes and human hepatoma cells was expected." (PMID 29513794, 2018). "In addition, ENPP1 might be involved in the occurrence and development of hepatocellular carcinoma by affecting the immune cell infiltration." (PMID 36199794, 2022).
metabolic syndrome (5 papers, 2012 to 2015). A cluster of metabolic risk factors for CARDIOVASCULAR DISEASES and TYPE 2 DIABETES MELLITUS. "For instance, NM_006208.2:c.2230 + 1G > A in the ENPP1 gene has been associated with metabolic syndrome in obese childhood and is observed in Mother, Son and Daughter." (PMID 26547235, 2015). "It is possible that the effect of ENPP1 on the risk of metabolic syndrome and the risk of CRC is highly dependent on additional environmental factors or modifiers." (PMID 23036011, 2012).
breast tumors (4 papers, 2013 to 2023). "Next, we formally tested the relative contribution of cancer- and host-derived ENPP1 on breast tumor growth and metastasis." (PMID 38117852, 2023). "We found that ENPP1-high cancer cells promote breast tumor growth by shunting the immunostimulatory cGAMP–STING pathway to the immunosuppressive eADO pathway, while fostering an angiogenic TME for tumor survival." (PMID 38117852, 2023). "In this study, we utilized a mouse model system where we observed impressive anti-metastatic effect when we removed ENPP1’s cGAMP hydrolysis activity that mirrors the survival advantage in patients with low ENPP1–expressing breast tumors." (PMID 38117852, 2023). "Here, using single-cell RNA-seq, we show that ENPP1 in both cancer and normal tissues drives primary breast tumor growth and metastasis by dampening extracellular 2′3′-cyclic-GMP-AMP (cGAMP)–STING-mediated antitumoral immunity." (PMID 38117852, 2023). "Patients in the METABRIC database with breast tumors expressing high levels of ENPP1 mRNA have a significantly worse disease-free survival rate, despite exhibiting a similar distribution across disease stages as the ENPP1-low group." (PMID 38117852, 2023). "Gene ENPP1 codes for protein ectonucleotide pyrophosphatase/phosphodiesterase 1, involved in cell proliferation and differentiation in breast tumors in humans." (PMID 32928114, 2020). "ENPP1 mRNA expression was also significantly higher in 53 human primary luminal-type breast tumours than 15 normal controls." (PMID 26065921, 2015). "Further, in clinical specimens, levels of Enpp1 were significantly elevated in human primary breast tumors relative to normal mammary epithelium, with highest levels observed in breast-bone metastasis as determined by qRT-PCR and immunohistochemical analysis." (PMID 23861746, 2013). "Finally, ENPP1 expression in breast tumors deterministically predicated whether patients would remain free of distant metastasis after pembrolizumab (anti-PD-1) treatment followed by surgery." (PMID 38117852, 2023).
Cole disease (4 papers, 2024 to 2025). "For example, the ENPP1 gene has 3 gene-disease assertions for arterial calcification generalized of infancy 1; hypophosphatemic rickets AR 2; and hypopigmentation-punctate palmoplantar keratoderma syndrome or Cole disease." (PMID 40496713, 2025).
glioma (4 papers, 2012 to 2024). A benign or malignant brain and spinal cord tumor that arises from glial cells (astrocytes, oligodendrocytes, ependymal cells). "ENPP1 is mostly overexpressed in certain tumor cells, e.g., high ENPP1 levels were observed in rat glioma cells, human astrocyte tumors, and also TNBC cells such as 4T1 and MDA-MB-231." (PMID 36235254, 2022).
hypercementosis (4 papers, 2012 to 2025). A regressive change of teeth characterized by excessive development of secondary cementum on the tooth surface. "Developmental studies of Ank KO and Enpp1 KO mice revealed dramatic hypercementosis in both PPi-deficient models." (PMID 40390808, 2025). "Reduced PPi levels and hypercementosis resulting from ENPP1 loss-of-function have been previously found in both mice and humans." (PMID 40390808, 2025). "Both Ank and Enpp1−/− mice featured a hypercementosis phenotype, indicating both PPi regulators function in controlling cementum formation." (PMID 22675556, 2012). "Conversely, mice lacking Ank or Enpp1 function exhibited hypercementosis with otherwise normal dental and periodontal structure." (PMID 30526676, 2018).
lung adenocarcinoma (4 papers, 2017 to 2025). A carcinoma that arises from the lung and is characterized by the presence of malignant glandular epithelial cells. "ENPP1 was found to be overexpressed in MDA-MB-231 (triple-negative breast cancer) with an abundance ratio of 3.55 (ratio with adjacent normal) as compared to A549 (lung adenocarcinoma), which had an abundance ratio of 0.58." (PMID 36235254, 2022).
nephrocalcinosis (4 papers, 2019 to 2025). Nephrocalcinosis is a disorder that occurs when too much calcium is deposited in the kidneys. "In ENPP1-deficient mice, recombinant ENPP protein prevented nephrocalcinosis and Achilles tendon calcification." (PMID 39199142, 2024). "When exposed to a procalcifying diet (high phosphate, vitamin D and low magnesium), Abcc6−/− and Enpp1−/− mice develop rapidly a nephrocalcinosis consisting in multiple calcium phosphate tubular plugs." (PMID 31861118, 2019).
ovarian carcinoma (4 papers, 2020 to 2026). A malignant neoplasm originating from the surface ovarian epithelium. "This study aimed at exploring the role of ENPP1 gene in ovarian carcinoma, the relationship with prognostic indicators and chemotherapy resistance, and investigates the possibility of molecular targeted therapy." (PMID 33635867, 2021). "In ovarian cancer tissues and ovarian cancer cell lines, mRNA and protein expression of ENPP1 was determined by qRT-PCR and Western blot." (PMID 33635867, 2021). "In present study, we conducted further cytological experiments on the role of ENPP1 in ovarian cancer cells." (PMID 33635867, 2021). "It further indicated that the proliferation, metastasis and invasion ability of ovarian cancer cells were significantly decreased after down regulating the expression of ENPP1 by PC-1 siRNA." (PMID 33635867, 2021). "ENPP1 was also highly expressed in ovarian cancer tissues and in epithelial ovarian cancer cell lines (A2780, CaoV3, OVCAR3, SKOV3 and 3ao)." (PMID 33635867, 2021). "After down-regulating the expression of ENPP1, the proliferation, migration and invasion of ovarian cancer cells were significantly inhibited, suggesting that ENPP1 could be a potential molecular therapeutic target." (PMID 33635867, 2021). "Similarly, our results also showed that ENPP1 was highly expressed in epithelial ovarian cancer cell lines (A2780, CaoV3, OVCAR3, SKOV3 and 3ao)." (PMID 33635867, 2021). "ENPP1 is increased in ovarian cancer and may promote migration." (PMID 32880385, 2020). "However, interference of ENPP1 expression with PC-1 siRNA can effectively inhibit EMT, thus effectively inhibiting the invasion and metastasis of ovarian cancer." (PMID 33635867, 2021).
X-linked hypophosphatemic rickets (4 papers, 2018 to 2025). "Although hearing loss is often observed in patients with X-linked hypophosphatemic rickets, it can also occur at an early age in patients with pathogenic variants in ENPP1, due to inner ear artery calcification or impaired inner ear development." (PMID 35966073, 2022).
Acidosis (3 papers, 2014 to 2024). Abnormal acid accumulation or depletion of base. "ENPP1 as well as ALPL activity are increased during acidosis whereby lactic acidosis exerts the strongest effect." (PMID 38195466, 2024). "In support of this notion, we observed prominent fields of resorption pits on the endosteal surfaces of Enpp1−/− bones and Enpp1−/− mice have increased levels of potassium ions, which can be a marker of acidosis, within the blood." (PMID 25260930, 2014).
Arterial stenosis (3 papers, 2022 to 2024). Narrowing or constriction of the inner surface (lumen) of an artery. "This research presented the vascular alterations of an ENPP1-mutanted patient, and while there is less calcification, intimal thickening may be the primary cause of arterial stenosis." (PMID 37153460, 2023). "Around 72% of patients with GACI develop myointimal hyperplasia and/ or arterial stenosis, which might be independent of plasma PPi levels, but is dependent on AMP and further adenosine generation of ENPP1." (PMID 39538190, 2024).
cardiac failure (3 papers, 2018 to 2025). "In this population of 84 individuals with ENPP1 Deficiency, the vast majority (76%) presented in infancy with cardiac insufficiency and respiratory distress requiring acute inpatient care." (PMID 40176950, 2025).
chondrocalcinosis (3 papers, 2015 to 2025). An acute episode of pain, swelling, and redness, sometimes associated with fever. "The association of ENPP1 variants with Chondrocalcinosis, is considered a minor determinant of the disease." (PMID 36276944, 2022).
colorectal cancer (3 papers, 2024 to 2025). A primary or metastatic malignant neoplasm that affects the colon or rectum. "We confirmed the scRNASeq data by flow cytometry for Enpp1 in the murine colorectal cancer cell lines MC38 and CT26." (PMID 39622844, 2024). "To confirm these data in an alternate murine model on a different genetic background, we used the CT26 colorectal carcinoma model which similarly lacks Enpp1 expression in BALB/c mice." (PMID 39622844, 2024). "Consistent with human colorectal carcinoma, Enpp1 was not significantly expressed in the CT26 or MC38 cancer cells in vivo." (PMID 39622844, 2024). "This dataset shows that as with our prior analysis, our two colorectal cancer cell lines MC38 and CT26 did not express Enpp1 and LLC did not express Enpp1." (PMID 39622844, 2024).
diffuse idiopathic skeletal hyperostosis (3 papers, 2022 to 2025). This syndrome is characterized by the association of ankylosing vertebral hyperostosis with hyperkeratosis of the soles and palms. "Clinical case reports have implicated the ENPP1 Y451C mutation in diffuse idiopathic skeletal hyperostosis patients, but its precise impact on bone mineralization and ectopic calcification remains unclear." (PMID 40535334, 2025). "Studies have also implicated ENPP1 deficiency in the development of ossification of the posterior longitudinal ligament (OPLL) and diffuse idiopathic skeletal hyperostosis (DISH)." (PMID 40535334, 2025).
insulin-dependent diabetes mellitus (3 papers, 2011 to 2024). "The deficiency of insulin and elevation of glucocorticoids in patients with type 1 diabetes may lead to increased Enpp1 expression, resulting in the accumulation of PPi." (PMID 29513794, 2018).
melanoma (3 papers, 2023 to 2024). A malignant, usually aggressive tumor composed of atypical, neoplastic melanocytes. "Moreover, melanoma secretome induces expression of a set of transcripts encoding for protein with tumor-promoting functions including CLEC17A, FR2, SMOX, TOX and ENPP1." (PMID 38239354, 2023).
arterial disease (2 papers, 2022 to 2025). "Given the high incidence of clinically significant arterial disease, it is expected that individuals with ENPP1 Deficiency would present with symptoms/signs around birth." (PMID 40176950, 2025).
Arthritis (2 papers, 2014 to 2024). Inflammation of a joint. "The loss of muscle mass in the quadratus femoris, a key target of exercise loading, is a likely consequence of the debilitating arthritis that the Enpp1−/− mice exhibit." (PMID 25368121, 2014). "This study demonstrated that the naturally derived quercetin and myricetin could effectively inhibit ENPP1 enzymatic activity and may offer health benefits in arthritis management." (PMID 38167594, 2024).
brain tumor (2 papers, 2020 to 2023). "To further test whether TCR-Ts could be activated by ENPP1 expressing cells, we then used U87MG brain tumor cells, which express higher level of ENPP1 than MB231 and similar level of HLA-A2." (PMID 32395117, 2020).
cardiomyopathy (2 papers, 2022 to 2024). A disease of the heart muscle or myocardium proper. "Our findings are also consistent with another recently published single-nuclear transcriptomic dataset in individuals with cardiomyopathy that demonstrated ENPP1 expression in myofibroblasts in end-stage cardiomyopathic hearts." (PMID 39454569, 2024).
chronic kidney disease (2 papers, 2015 to 2018). Impairment of the renal function secondary to chronic kidney damage persisting for three or more months. "Polymorphisms in the ENPP1 gene have also been associated with an increased risk of end-stage renal disease early in the course of T1D." (PMID 26302420, 2015).
coronary artery disease (2 papers, 2018). "Meta-analysis of the relationships between ENPP1 genetic polymorphism and the coronary heart disease." (PMID 29979387, 2018). "Previous studies suggested an association between K121Q (rs1044498 C > A) in ecto-nucleotide pyrophosphatase phosphodiesterase 1 (ENPP1) gene and the risk of coronary heart disease (CHD), but the results have been inconsistent." (PMID 29979387, 2018). "In this study, the correlation of the ENPP1 serum level with CAC was clinically evaluated for the first time in patients with coronary artery disease." (PMID 30276146, 2018).